PAX4 (paired box 4)
Diseases named in the same sentence as PAX4 in open-access papers (continued):
Sharing a sentence is not in itself a finding about the gene and the disease.
Zinc deficiency (2 papers, 2017 to 2021). A deficiency of the essential metal Zinc; an essential cofactor for many enzymes. "Significant changes in RNA expression of genes that regulate zinc homeostasis, response to oxidative stress and insulin production (including zip1, znt7, nrf2, ogg1, pax4, and insa) were found in zinc deficient, or zinc deficiency and arsenic exposed embryos." (PMID 28837703, 2017). "Modest, but significant effects of zinc deficiency and/or arsenic exposure were also found in developing embryos on the expression of genes that regulate zinc transport, response to oxidative stress, and insulin production (including zip1, znt7, nrf2, ogg1, pax4, and insa)." (PMID 28837703, 2017).
cardiomyopathy (1 paper, 2018). A disease of the heart muscle or myocardium proper. "This was further proved in our PAX4 KO rabbits, for typical DM associated phenotypes were also observed in the PAX4−/− rabbits, including diabetic nephropathy, hepatopathy, myopathy and cardiomyopathy." (PMID 29950431, 2018). "Furthermore, DM associated phenotypes including diabetic nephropathy, hepatopathy, myopathy and cardiomyopathy were also observed in the homozygous PAX4 KO rabbits but not in the wild type (WT) controls and the heterozygous PAX4 KO rabbits." (PMID 29950431, 2018).
diffuse large B-cell lymphoma (1 paper, 2017). "Moreover, demethylation of the human PAX4 promoter region located −1347 to −1103 bp from translation initiation site has been linked to aberrant expression of PAX4 in lymph nodes of patients with diffuse large B cell lymphoma (DLBCL) as well as in several hematological cell lines." (PMID 28282933, 2017).
Hypertension (1 paper, 2016). The presence of chronic increased pressure in the systemic arterial system. "We find a significant interaction effect of the GCK and PAX4 genes on hypertension in the GAW19 data." (PMID 27980658, 2016). "We find that the genes GCK and PAX4, formerly known to be found within similar coexpression and pathway networks but without specific direct interactions, do, in fact, show significant joint interaction effects for hypertension." (PMID 27980658, 2016). "In addition, GCK and PAX4 are not known to specifically interact toward hypertension." (PMID 27980658, 2016).
lymphoma (1 paper, 2021). A malignant (clonal) proliferation of B- lymphocytes or T- lymphocytes which involves the lymph nodes, bone marrow and/or extranodal sites. "A previous study demonstrated that PAX4 is aberrantly expressed in primary lymphomas." (PMID 34162761, 2021).
pancreatic cancer (1 paper, 2025). "Among them, the expression of PAX4 was associated with the proliferation and differentiation of pancreatic cancer cells, and PAX4 may promote tumor development by regulating the cell cycle and promoting cell proliferation." (PMID 40644416, 2025).
prostate carcinoma (1 paper, 2011). A carcinoma that arises from epithelial cells of the prostate gland. "In particular, RegNetB identified the regulators PAX4, BACH1, BACH2, MAZ and TAF8 as playing a central role in this prostate cancer gene expression data set." (PMID 21682879, 2011).
steatosis (1 paper, 2018). Increased lipid within the cytoplasm of cells. "Significantly, the PAX4+/− rabbits only exhibited slight hepatocyte steatosis and vacuolation of renal tubular epithelial cells." (PMID 29950431, 2018).
tumor (11 papers, 2009 to 2025). "Pax4 expression was significantly correlated to tumor size (P = 0.0371), lymph node metastasis (P = 0.0029) and TNM stage (P = 0.0039)." (PMID 34162761, 2021). "miR-27b-3p was confirmed with the binding site with PAX4 using ChIP assay and served as a tumor suppressor that inhibiting GC cell growth and metastasis, and reversed the effect of PAX4." (PMID 34162761, 2021). "In fact, the average volume and weight of tumor in the si-PAX4 group were markedly decreased compared to si-NC group." (PMID 34162761, 2021). "PAX4/ miR-27b-3p/Grb2 regulatory loop plays a significant role in GC tumor progression, which indicates that potential therapy biomarkers need to be further investigated." (PMID 34162761, 2021). "This work provides the first clear that PAX4 plays a significant role GC, and will give us more inspiration on tumor target therapy." (PMID 34162761, 2021). "Taken together, we concluded that up-regulated PAX4 levels can accelerate GC cell growth, migration and invasion, and promote GC tumor growth, functioned as a crucial oncogene both in vitro and in vivo." (PMID 34162761, 2021). "Then protein levels of paired box genes (Pax-4 and Pax-6) were examined by western blotting, which were considered to promote tumor growth." (PMID 31636510, 2019). "These target genes are known to participate in tumor progression, but the suggested regulatory roles of PAX4, BACH1, BACH2, MAZ and TAF8 in the process is new." (PMID 21682879, 2011). "Next, 21 days after injection, we observed that knockdown of PAX4 suppressed tumor growth." (PMID 34162761, 2021). "However, in the PAX4 ov group, the average volume and weight of tumor were significantly increased compared to the NC group." (PMID 34162761, 2021). "Hence, these findings validate our hypothesis that miR-27b-3p is able to reverse GC cell promotion and metastasis mediated by PAX4 and can serve as a tumor suppressor." (PMID 34162761, 2021). "Furthermore, as a potential tumor suppressive function for PAX4 has recently been reported, we speculate that disruption of PAX4 could compromise TGF-β-mediated growth inhibition and contribute to ovarian carcinogenesis." (PMID 19615063, 2009). "In the same way, a study described PAX4 as a key regulator of tumor vascularization, and interfering with its signal improved CAR-T cell influx to the tumor." (PMID 33800593, 2021). "From this, therefore, we hypothesized that in the pathological process of LGG, ZNF800 activates the cell cycle by interacting with PAX4, SOX4, and so on, from promoting malignant tumor progression." (PMID 40644416, 2025).
cancer (9 papers, 2010 to 2023). A tumor composed of atypical neoplastic, often pleomorphic cells that invade other tissues. "PAX4 plays critical roles during both fetal development and cancer growth." (PMID 22829753, 2012). "ZEB1, HES1, NR6A1, PATZ1, PAX4 and MTF1—have a reported oncogenic role in cancer types other than HCC." (PMID 33541355, 2021). "Therefore, we hypothesized that PAX4 expression in GC cells may influence cancer cell progression." (PMID 34162761, 2021). "We also identified potential transcriptional factors with known oncogenic roles in HCC, e.g. ZEB1, or in other cancer types, e.g. HES1, NR6A1, PATZ1, PAX4 and MTF1, in GE1-HCC." (PMID 33541355, 2021). "Six multiple interacting TFs were found to have common functions between immune systems and cancer tissues, including CEBPGAMMA:NKX25:PLZF, CEBPGAMMA:PAX4:PLZF, CP2:NFY:PAX4, FOXJ2:PAX4:POU3F2, CEBPGAMMA:PAX4:PLZF, and FOXJ2:HNF3:PAX4." (PMID 20085649, 2010). "Paired box gene 4 (PAX4) is a transcription factor which is a member of PAX family located on chromosome 7 and regulates fetal development, cancer growth, commitment of progenitor cells to various islet cells and also represses the promoter activity of insulin and glucagon." (PMID 29867778, 2018).
infection (2 papers, 2008 to 2013). The state of being infected such as from the introduction of a foreign agent such as serum, vaccine, antigenic substance or organism. "Interestingly, Math6 mRNA expression declined 48 h post-infection, whereas levels of other Neurog3-induced mRNAs were maintained (Pax4, NeuroD1) or remained elevated (somatostatin) through 72 h." (PMID 18560595, 2008). "Math6 mRNA was expressed at low levels in untreated mPAC cells and was induced 12 h after infection with AdCMV-NEUROG3, concomitantly with appearance of Pax4 mRNA and prior to induction of NeuroD1 mRNA, two known direct targets of Neurog3." (PMID 18560595, 2008).
metabolic disease (1 paper, 2021). A congenital disorder (due to inherited enzyme abnormality) or acquired (due to failure of a metabolically important organ) disorder resulting from an abnormal metabolic process. "Studies of PAX4 have mainly focused on the development of pancreatic β, δ-cells and metabolic diseases, though it has been reported PAX4 expression is dysregulated in human epithelial cancers." (PMID 34162761, 2021).
PAX4 also shares sentences with these, for which no sentence is quoted: Allergy (1 paper); alopecia (1); aniridia (1); cervical cancer (1); Cognitive impairment (1); diabetes insipidus (1); diabetic nephropathy (1); genetic disorder (1); Glucose intolerance (1); hepatocellular carcinoma (1); hepatopathy (1); Huntington disease (1); Immunodeficiency (1); Impaired glucose tolerance (1); ischemic stroke (1); Metabolic (1); MODY type 9 (1); myopathy (1); optic atrophy (1); otofaciocervical syndrome (1); pancreatic disease (1); renal coloboma syndrome (1); vasculitis (1); Waardenburg syndrome (1); Wolfram syndrome (1).